PLAAT2 (phospholipase A and acyltransferase 2)
Description:
Exhibits both phospholipase A1/2 and acyltransferase activities. Shows phospholipase A1 (PLA1) and A2 (PLA2) activity, catalyzing the calcium-independent release of fatty acids from the sn-1 or sn-2 position of glycerophospholipids. For most substrates, PLA1 activity is much higher than PLA2 activity. Shows O-acyltransferase activity, catalyzing the transfer of a fatty acyl group from glycerophospholipid to the hydroxyl group of lysophospholipid. Shows N-acyltransferase activity, catalyzing the calcium-independent transfer of a fatty acyl group at the sn-1 position of phosphatidylcholine (PC) and other glycerophospholipids to the primary amine of phosphatidylethanolamine (PE), forming N-acylphosphatidylethanolamine (NAPE), which serves as precursor for N-acylethanolamines (NAEs). Catalyzes N-acylation of PE using both sn-1 and sn-2 palmitoyl groups of PC as acyl donor. Exhibits high phospholipase A1/2 activity and low N-acyltransferase activity.
Synonyms: HRASLS2; FLJ20556; PLAAT-2; PLA1/2-2
Tractability: Small molecule: a high-quality ligand is known. Antibody: UniProt predicts a signal peptide or a membrane-spanning region. PROTAC: ubiquitination databases record sites on it; a small molecule that binds it is known.
Target class: Enzyme; Transferase
Gene: Protein-coding gene on chromosome 11 (63,552,770 to 63,563,379, reverse strand). Ensembl gene ENSG00000133328.
Subcellular location: Cytoplasm; Membrane
Subcellular location (Human Protein Atlas): Mitochondria
Pathways (Reactome):
Metabolism: Acyl chain remodelling of PE
Gene Ontology:
Molecular function: acyltransferase activity, transferring groups other than amino-acyl groups; phospholipase A1 activity; phospholipase A2 activity; protein binding; acyltransferase activity
Biological process: N-acylphosphatidylethanolamine metabolic process; phosphatidylethanolamine acyl-chain remodeling
Cellular component: cytoplasm; cytosol; membrane
Genetic constraint (gnomAD): Loss-of-function variants: 10 observed, 10.82 expected, observed/expected ratio (o/e) 0.92, 90% interval 0.57 to 1.55. The upper end of that interval is the gene's LOEUF score, 1.55, which puts it in group 6 of 6, group 1 being the genes least tolerant of losing a copy. Missense variants: 149 observed, 200.84 expected, observed/expected ratio (o/e) 0.74, 90% interval 0.65 to 0.85. Synonymous variants: 73 observed, 84.46 expected, observed/expected ratio (o/e) 0.86, 90% interval 0.71 to 1.05.
Homologues: Orthologues: chimpanzee PLAAT2 (99% identical), macaque PLAAT3 (75% identical), rabbit PLAAT2 (73% identical), guinea pig PLAAT2 (64% identical), zebrafish lratb.2 (30% identical). Paralogues in human: PLAAT3 (68% identical), PLAAT4 (49% identical), PLAAT5 (44% identical), PLAAT1 (43% identical), LRAT (29% identical), LRATD2 (28% identical), LRATD1 (20% identical).
Diseases named in the same sentence as PLAAT2 in open-access papers:
PLAAT2 is named in the same sentence as 5 diseases in open-access papers, as found by Europe PMC text mining. Sharing a sentence is not in itself a finding about the gene and the disease. The quoted sentences say what the papers report.
tumor (4 papers, 2014 to 2026). "In vivo xenograft models further validated the tumor-suppressive role of PLAAT2." (PMID 41851102, 2026). "PLAAT2 functions as a tumor suppressor in GC by recruiting TRIM32 to facilitate cMyc ubiquitination and impair MEK/ERK-driven oncogenic signaling, highlighting the PLAAT2/TRIM32/cMyc axis as a potential therapeutic target." (PMID 41851102, 2026).
PLAAT2 also shares sentences with these, for which no sentence is quoted: cervical cancer (1 paper); gastric cancer (1); infection (1); Obesity (1).